INS (insulin)
Diseases named in the same sentence as INS in open-access papers (continued):
Sharing a sentence is not in itself a finding about the gene and the disease.
Insulin resistance (continued). "Also, because serum insulin levels were not determined in fasting subjects and thus could not be used, insulin resistance was not assessed in this study as a possible factor impacting the association between thyroid dysfunction and NAFLD." (PMID 26276551, 2015). "Finally, given the controversy over circulating ZAG levels and insulin sensitivity in the clinical setting of obesity, plasma ZAG protein levels were measured in lean subjects (BMI ranging from 21.07 to 25.6) classified according to their insulin resistance, assessed by HOMA-IR." (PMID 26068931, 2015). "In addition, the insulin resistance of TLR5−/− mice is not entirely dependent on increased food consumption or adiposity seeing that the lean TLR5−/− mice after 12 weeks of food restriction regimen still exhibited a decreased response to exogenous insulin." (PMID 26681840, 2015). "Although the presence of the insulin-sensitive fat transplant might increase the FAHFAs in fat-transplanted InsrP1195L/+/HFD mice, our present results suggest that normal glycerol metabolism in WAT is also important for the maintenance of glucose homeostasis under insulin resistance." (PMID 26615883, 2015). "In summary, our results shed the light on the possible role of DNAJB3 in improving insulin sensitivity and glucose uptake through JNK repression and suggest that DNAJB3 could be a potential target for therapeutic treatment of obesity-induced insulin resistance." (PMID 26400768, 2015). "Similarly, C3H mice, which lack Pparγ expression in the liver, did not enhance hepatic Cd36, Fabp4, and Mogat1 expression on the SRD diet or in response to liver insulin perfusions, and furthermore, they did not develop hepatosteatosis and hepatic insulin resistance in response to the SRD." (PMID 26085100, 2015). "This emphasises the important role of insulin resistance in the pathophysiology of diabetic dyslipidaemia, which is also highlighted by the presence of lipid abnormalities typical of diabetic dyslipidaemia in non-diabetic insulin-resistant first-degree relatives of patients with type 2 diabetes." (PMID 25725623, 2015). "Furthermore, as insulin sensitivity and tolerance to glucose were not tested in the present study, it is possible that insulin resistance may have correlated with worse outcome." (PMID 26239227, 2015). "In summary, PCOS subjects with elevated insulin and testosterone levels, showed higher circulating levels of miR-93 and miR-223 compared to age and weight matched controls, though the elevation in the miRNA levels was not related to either insulin resistance or hyperandrogenaemia." (PMID 26582398, 2015). "Severity of insulin resistance should vary depending on the age of db/db mice, which may in turn affect the function of ANGPTL2 because adipocytes may expose more pro-inflammatory environment and produce more adipokines, leading to more insulin resistant state under more obese condition." (PMID 26132105, 2015). "Therefore, from the findings in this study, we propose that SA may be able to prevent insulin resistance through transcriptional regulation of insulin signaling genes and nontranscriptional mechanisms, depending on the concentration used." (PMID 26688813, 2015). "The data obtained on insulin resistance in our study are not in agreement with the study where anti-diabetic properties of 4-hydroxy isoleucine, the active compound in Fenugreek were seen for its insulinotropic action and for extrapancreatic insulin-sensitizing effects." (PMID 26436069, 2015). "The changes in insulin signaling may be induced by pro-inflammatory cytokines and adipokines secreted from both the adipose tissue and placenta of mothers with GDM, which have been previously implicated in insulin resistance among non-pregnant populations." (PMID 26244062, 2015).
Insulin resistance (continued). "Furthermore, since insulin was already shown to regulate GLP-1 release from L cells, our results suggest that the negative correlation between insulin resistance and GLP-1 secretion might also involve insulin resistance in cells secreting GLP-1." (PMID 24648662, 2014). "Studies have also shown that bilateral cervical vagotomy of the liver can induce insulin resistance and that this phenomenon could be reversed by acetylcholine, which stimulates hepatic insulin-sensitizing substance (HISS) secretion to improve peripheral tissue insulin activity." (PMID 25024728, 2014). "However, our results do not reveal any association of MAP3K8 expression with markers of insulin sensitivity in human subjects and do not support a crucial role for MAP3K8 as an important regulator in the development of insulin resistance during obesity in mice." (PMID 24586913, 2014). "Moreover, we have demonstrated that insulin secretory functions, such as homeostasis model assessment-pancreatic beta-cell function (HOMA-β) and insulinogenic index, but not insulin resistance, are negatively associated with GA/A1c ratio in patients with type 2 diabetes (T2D)." (PMID 24586809, 2014). "Leptin and adiponectin were studied because of the evidence that leptin affected insulin resistance in mice independent of changing body weight, whereas adiponectin promoted the survival and function of islet β cells and improved peripheral insulin sensitivity." (PMID 24736781, 2014). "However, considering the unaltered mTOR activation level and prevention of the HFD-induced insulin resistance by reducing gluconeogenesis, we believe that the effect of changes in protein level is not likely the primary contributor to the changes in insulin sensitivity in this study." (PMID 25055153, 2014). "Hence, the isolated detection of reduced insulin sensitivity by HOMA-IR and ISI OGTT, without corresponding alterations in ISI clamp-derived indices, could reflect a selective hepatic insulin resistance in minor A-allele carriers of SNP rs8046707." (PMID 25025664, 2014). "According to this study in Chinese type 2 diabetes patients, the level of 25-(OH)D may not be associated with HOMA-B, an index of pancreatic beta cell function derived from fasting insulin and glucose concentrations, and may not be associated with HOMA-IR, an index of insulin resistance." (PMID 24868538, 2014). "Moreover, during the hyperinsulinemic episodes in patients with MS and insulin resistance, despite to the high levels of insulin detected, a significant proportion of the hormone could not be biologically available because it is bound to SIR." (PMID 24995000, 2014). "Although the insulin secretion conditions of each participant were not measured on entry into the study, we may hypothesize that insulin glargine treatment improves the insulin resistance of patients with T2D mellitus; this hypothesis is consistent with previous studies." (PMID 24944613, 2014). "However, because the Matsuda and insulinogenic indices were originally derived from the results of OGTTs, they may not be appropriate for assessing insulin resistance and acute insulin secretion during MTTs." (PMID 25360162, 2014). "Due to the intimate involvement of ROS in multiple aspects of insulin signalling, unraveling the timeline and dynamics of ROS production within the context of insulin resistance will help to determine whether or not ROS is a viable target for the treatment of metabolic disease." (PMID 24672550, 2014). "However, in our research plasma insulin level was maintained beyond 75 mIU L−1, and this should be sufficient to suppress most of the hepatic glucose production in the subjects without extreme insulin resistance." (PMID 23934358, 2014). "Interestingly, these results suggested that GS might induce insulin resistance also in cells which are not considered classical targets for insulin-mediated activities." (PMID 24648662, 2014).
Insulin resistance (continued). "We suggest that HOMA-IR, rather than fasting plasma glucose and fasting plasma insulin levels alone, could be a valuable tool to identify patients with subclinical insulin resistance, which could be relevant for primary prevention and for high risk patient screening." (PMID 23497533, 2013). "In a word, resistin could induce hepatic insulin resistance by inhibiting the phosphorylation of Akt and GSK3, and its effect on insulin sensitivity is opposite to those reported for the adipocyte-secreted hormone adiponectin, which increases insulin sensitivity of the same liver-specific functions." (PMID 23762871, 2013). "Indeed, dogs fed a high fat diet for 12 weeks developed insulin resistance, which was followed by a transient increase in acute insulin response (AIR) to an intravenous glucose tolerance test (IVGTT), and a sustained reduction in insulin clearance to maintain glucose homeostasis." (PMID 24194886, 2013). "However, the lack of difference between groups in the fall in glucose concentration after an insulin bolus, together with decreased insulin secretion after a glucose load in the U group indicate that insulin resistance is unlikely to have contributed to the glucose intolerance seen in our animals." (PMID 23613779, 2013). "However, assessment of beta–cell function among individuals with different insulin sensitivity is not an easy task, because in non‐diabetic humans, insulin resistance is accompanied by a rise in insulin secretion, in order to compensate for the reduced action of insulin on responsive tissues." (PMID 24146977, 2013). "Whilst obesity related adipose tissue fibrosis may well attribute to insulin resistance as also shown by increased levels of ECM components such as collagen VIalpha3, the multifunctional protein SPARC appears to influence more than one pathway of glucose and insulin metabolism." (PMID 23840838, 2013). "Therefore, the absence of improvement in insulin sensitivity in this study might be due to mechanisms of insulin resistance in PCOS that are distinct from those in type-2 diabetes." (PMID 23690868, 2013). "Thus, it could be that our model using 30 mg/kg STZ mimics a later stage in type 2 diabetes-insulin resistance disease progression, when β-cell function starts to become compromised and no longer matches the increased demand for insulin." (PMID 24063408, 2013). "Thus, the exposure to a prenatal LOW level of nutrition affected insulin signalling molecules only in muscles of lambs, but not in adult sheep, although signs of insulin resistance were clearly revealed only in the adult sheep and not in the lambs, as previously reported." (PMID 23755234, 2013). "In addition to insulin resistance and impaired function of pancreatic β-cells in patients with T2DM, this study focused on insulin secretion affected by 5-HT2CR, which has been suggested the possibility that an abnormal 5-HT system could also affect regulation of energy metabolism." (PMID 23349838, 2013). "Hence, the clinical markers such as QUICKI, those are estimated by blood insulin levels, might not accurately reflect the sevirity of insulin resistance in these patients." (PMID 22496878, 2012). "The current findings are based on analysis of fasting insulin, rather than an index of insulin resistance such as homeostasis model assessment of insulin resistance (HOMA-IR), which might have more relevance to type 2 DM in which insulin resistance is the cardinal feature." (PMID 22095452, 2012). "Since the mechanisms responsible for the alleviation of insulin resistance under the high level of FFA still remain unclear, we sought to evaluate the pharmacological effect of APS and to investigate in more detail its mechanism by using an insulin-resistant cell model induced by palmitate." (PMID 22728372, 2012).
Insulin resistance (continued). "Insulin sensitivity was not measured in DiOGenes but both the high-protein and the high GI diets significantly increased markers of low-grade inflammation, which could result in worsening of insulin resistance." (PMID 24278690, 2012). "Therefore, the adjustment for fasting insulin levels may not have adequately captured the influence of hyperinsulinemia or insulin resistance." (PMID 23066943, 2012). "Furthermore, our initial study design did not allow for the examination of insulin levels and insulin resistance, although insulin resistance may be an important link between low GH levels and NAFLD." (PMID 22952901, 2012). "Yin also in type 2 diabetic patients reported that Berberine may change the body fat distribution which leads to decreasing the insulin resistance and increasing the insulin sensitivity and also to the improvement of insulin secretion, but the mentioned study had no control group." (PMID 24250489, 2012). "Neither fasting nor fed NEFA levels differed among the three ZDF groups despite large differences in insulin resistance, suggesting that the increased insulin sensitivity may not be directly related to plasma NEFA in this model, but rather by other factors such as circulating adipokines." (PMID 23146593, 2012). "If this finding of worsening insulin sensitivity with high serum chromium levels is confirmed then it is possible that the widespread use of chromium supplements may be contributing to, rather than ameliorating, insulin resistance in the population." (PMID 23194380, 2012). "Furthermore, if contrary to the widely held belief, a systemic increase in cytokine concentration does not necessarily precede insulin resistance, more work needs to be done in the adolescent human to identify other possible mechanisms that contribute to insulin resistance." (PMID 22682228, 2012). "Finally, we could not explain the influence of insulin, and further study is needed to adjust for insulin resistance." (PMID 21492487, 2011). "Insulin secretagogues such as repaglinide, and sulphonylureas (glimepiride, gliclazide, glibenclamide) are safe, but may not be effective in the face of severe insulin resistance." (PMID 21232158, 2011). "In addition, while it was accompanied by insulin oversecretion in saline-infused animals (P<0.05), this did not occur in OT-infused rats, suggesting that OT might protect against HFD-induced glucose intolerance and insulin resistance." (PMID 21980491, 2011). "We found that the inhibitory effect of FFAs upon insulin-stimulated activation of hepatic Akt and its action upon glucose metabolism may indeed be the result of excessive PP2A activity, and that PP2A is also hyperactive in an animal model of insulin resistance." (PMID 22087313, 2011). "Thus, while it is well established that treatment of insulin resistance has beneficial effects in patients with type 2 diabetes, it is becoming increasingly clear that enhanced insulin sensitivity is also therapeutically important in nondiabetic individuals with insulin resistance." (PMID 20814545, 2010). "Although an inverse association between 25(OH)D and insulin secretion may seem contradictory to the hypothesis that vitamin D is necessary for β-cell synthesis of insulin, subjects with insulin resistance, but not T2DM, often experience compensatory hyperinsulinemia." (PMID 20011094, 2010). "Initial insulin resistance (resulting from the pregnancy hormones in the case of gestational diabetes) develops into gestational or type 2 diabetes when pancreatic β-cell function is no longer able to maintain sufficient levels of insulin to counter the effects of the insulin resistance." (PMID 18782806, 2009). "Thus, wild type C57BL/6 mice fed the type of high-cholesterol diet used in the present study (0.15% cholesterol/4.3% fat) do not typically develop insulin resistance, making it unlikely that the vascular pathology observed here can be ascribed to insulin resistance." (PMID 19852847, 2009).
Insulin resistance (continued). "Finally, a prolonged exposure to insulin (a typical conditionin hyperinsulinemic patients) may result in a degradation of IRS protein.All together, these data support IRS-1 and IRS-2 as crucial players in thedevelopment of insulin resistance." (PMID 18604303, 2008). "Third, we may not have captured insulin resistance optimally with BMI, waist and insulin." (PMID 17958881, 2007). "Insulin resistance was assessed using the homeostasis model assessment index (HOMA-IR), and patients with T2DM were classified as insulin-resistant or non-insulin-resistant based on established criteria." (PMID 41641247, 2026). "A recent examination of lean PCOS patients revealed no change in insulin-stimulated Akt phosphorylation in skeletal muscle, nor any difference in GLUT4 protein levels, despite whole-body insulin resistance in hyperinsulinemic-euglycemic clamps." (PMID 40013621, 2025). "Given that leptin levels are increased in MASLD patients, and leptin promotes insulin resistance, we consider the negative relationship between FGF21 and LEPR as highly suggestive for FGF21 to improve insulin sensitivity by dampening leptin signalling." (PMID 39962359, 2025). "Homeostatic Model Assessment for Insulin Resistance (HOMA-IR), a widely used index, is calculated from fasting glucose and endogenous insulin concentrations and, therefore, reflects insulin sensitivity in the liver rather than muscle." (PMID 39998445, 2025). "In treating adult T2DM, insulin therapy has become a widely recognized approach; however, in pediatric T2DM patients, insulin therapy has not shown significant effects on insulin resistance." (PMID 40735644, 2025). "Together, the data show that HFD-induced insulin resistance is characterized by alterations in GLUT4 targeting during fasting, so that the effect of TUG to trap GLUT4 in an intracellular, insulin-responsive pool of GSVs is no longer observed." (PMID 40631311, 2025). "HFD-fed mice showed higher systemic insulin levels than KD-fed mice, regardless of genotype, suggesting HFD-induced insulin resistance." (PMID 40864559, 2025). "Significantly, calcium ions, being a crucial second messenger in glucose-stimulated insulin secretion (GSIS), any imbalance in their homeostasis not only impairs β-cell function but also exacerbates peripheral insulin resistance through multiple mechanisms." (PMID 41301787, 2025). "Additionally, one study of MetR for 14 weeks in leptin‐deficient mice observed significant decreases in fasting insulin and HOMA‐IR, without changes in fasting blood glucose, which suggested that improved insulin resistance due to MetR may be independent of leptin and changes in glucose levels." (PMID 40526038, 2025). "Although these parameters can mediate insulin resistance, this study did not propose a direct link between CVD and improved insulin action." (PMID 39998445, 2025). "D2 receptor expression showed a positive correlation with homeostatic model assessment for insulin resistance (HOMA-IR), fasting insulin, and HbA1c, but a negative correlation with insulin sensitivity." (PMID 40869170, 2025). "Another significant limitation of this study is that insulin was not measured, which prevented the calculation of the HOMA index and a direct evaluation of insulin resistance." (PMID 40487022, 2025). "In Wistar-Kyoto rats fed a fructose diet, mangiferin reduced plasma insulin and non-esterified fatty acid (NEFA) levels, mitigating adipose tissue insulin resistance without affecting fructose intake, fat accumulation, or hypertension." (PMID 40647096, 2025). "In the state of insulin resistance induced by T2DM, insulin fails to suppress glucose production and instead significantly elevates lipid levels, ultimately resulting in hyperglycemia and hypertriglyceridemia." (PMID 40666176, 2025).